CXCL12 (C-X-C motif chemokine ligand 12)
Diseases named in the same sentence as CXCL12 in open-access papers (continued):
Sharing a sentence is not in itself a finding about the gene and the disease.
lung carcinoma (continued). "This promotes a positive feedback loop in which lung cancer cells upregulate the CXCL12/CXCR4 pathway to further increase ERα expression." (PMID 41463203, 2025). "CXCR4-expressing lung cancer cells are more metastatic because the receptor promotes chemotactic migration towards CXCL12-enriched sites, allowing invasion, extravasation, and colonization." (PMID 41383468, 2025). "In this review, we explore the function of the CXCR4/CXCL12 axis in lung cancer metastasis and its therapeutic potential for stopping tumor progression and strengthening cancer treatment." (PMID 41383468, 2025). "Lung cancer cells express specific chemokines (such as CXCL12/14/16, CCL7/22, CX3CL1, and XCL1) and their corresponding receptors." (PMID 39512767, 2024). "The qPCR results showed that iCAFs and CAFs expressed higher level of CXCL12 than NFs, and ELISA results indicated that both iCAFs and CAFs secreted higher amount of CXCL12 than lung cancer cells." (PMID 39759028, 2024). "Collectively, our data demonstrated that iCAFs enhanced lung cancer cell migration and invasion via CXCL12-mediated AKT/NF-κB pathway." (PMID 39759028, 2024). "Clinical lung cancer tissue samples also reveal a positive correlation between elevated CXCL12 and positive p-STAT3 expression and the malignant progression of lung cancer." (PMID 38920657, 2024). "Baseline pain is an independent prognostic factor affecting the efficacy of ICIs in lung cancer, potentially through CXCL12-mediated inflammation promotion and immunosuppression." (PMID 39654896, 2024). "Taken together, these results demonstrated that iCAFs promoted lung cancer cell migration and invasion via CXCL12 secretion." (PMID 39759028, 2024). "Our results demonstrated that iCAFs facilitated lung cancer cell growth and invasion via CXCL12 secretion." (PMID 39759028, 2024). "CD248-expressing CAFs-derived CXCL12 mediated M2-polarized macrophages and promoted lung cancer progression." (PMID 39759028, 2024). "Next, we studied the role of CXCL12 in cell activities by adding recombinant CXCL12 to culture medium and found that CXCL12 boosted the proliferation, migration, and invasion of lung cancer cells." (PMID 39759028, 2024). "CAFs interact with tumor cells via secretion of various growth factors or cytokines, and several studies have shown that CAFs secrete CXCL12 to facilitate tumor progression; this drove us to evaluate the role of CXCL12 in iCAFs’ effect on lung cancer cells." (PMID 39759028, 2024). "On the other hand, the activated CAFs facilitated the metastasis potential of lung cancer cells through CXCL12 release and downstream AKT/nuclear factor κB (NF-κB) pathway activation." (PMID 39759028, 2024). "Previous studies have demonstrated that all major subtypes of NSCLC tumors express CXCR4 and that the main sites of lung cancer metastasis, including bones, liver, adrenal glands, and brain, express high levels of CXCL12." (PMID 37227446, 2023). "The stromal cell-derived factor 1 (SDF-1/CXCL12) chemokine has been also examined as a potential target for therapeutic intervention in patients with colorectal, breast, and lung cancer." (PMID 38239363, 2023). "We next tested the ability of CXCL12–Beva to promote uptake in other cell lines, including breast and lung cancer lines, and found that these cells also significantly take up VEGF." (PMID 36138170, 2023). "Spheroids composed of 344SQ murine lung cancer cells with either control or Ube2t-, Tk1-, Cxcl12-, and Kpna2-knockdown CAFs were seeded into collagen gel, and spheroid invasion was then monitored for 2 days." (PMID 35884546, 2022). "It has been reported in an experimental study that blocking CXCR4 inhibited the proliferation of lung cancer cells and the migration to CXCL12." (PMID 35729596, 2022).
lung carcinoma (continued). "Again, many of the immune-modulatory genes differentially expressed in the mouse model were site-specifically recapitulated, e.g., higher CCL2, CXCL5, CXCL9, CXCL11, CXCL14, CXCL17, and IDO1 in lung cancers and higher CXCL12, FGL1, and LAG3 in liver cancers." (PMID 33985562, 2021). "The CCL20 was expressed in cancer cells and macrophages in lung cancer tissues, while the CXCL12 was expressed by fibroblasts in lung cancer tissues." (PMID 35069521, 2021). "Another tumour-suppressive miRNA, namely, miRNA-101, was also found to directly target CXCL12, thereby impairing the ability of CAFs to stimulate lung cancer cell proliferation and metastasis as well as stem cell sphere formation." (PMID 30944831, 2019). "The effects of CXCL12 in many cancer types, including its role in promoting local invasion and distant metastasis from lung cancer metastasis, have been described." (PMID 31718601, 2019). "A role for the CXCL12/CXCR4/7 chemokine–chemokine receptor axes has also been proposed in mouse lung cancer metastasis-induced by lung carcinoma cell transplantation most likely by shaping infiltrated immune cell population and promoting angiogenesis." (PMID 30832375, 2019). "In this review, the pathologic roles that CXCL12/CXCR4 play in lung cancer propagation are presented." (PMID 30257500, 2018). "CXCL12 evokes mobilization of lung cancer cells and confers a high capacity for self-renewal on these cells." (PMID 25871388, 2015). "The analysis confirmed that the CXCL12/CXCR4 biological axis can induce lung cancer cell proliferation." (PMID 24944647, 2014). "Increasing evidence also indicates that the CXC chemokine receptor 4 (CXCR4)/chemokine CXC motif ligand 12 (CXCL12) chemokine axis is important for the cell invasion and migration of lung cancer." (PMID 24944647, 2014). "The proliferation of the A549 lung cancer cell line in response to CXCL12 was found to be reduced by the downregulation of CXCR4 expression by the pBSilence1.1-siRNA-CXCR4 vector, as determined by MTT assay." (PMID 24944647, 2014). "If CXCR4 truly mediates metastasis, when lung cancer cells enter the blood or lymphatic systems, they would preferentially migrate and adhere to areas with high expression of CXCL12." (PMID 23322021, 2013). "CXCL12 was shown to increase the migration of lung cancer cells through the CXCR4-mediated activation of ERK, which in turn activates IKKa/b and NF-κB, resulting in the activations of integrins (ITGB1 and ITGB3)." (PMID 23322021, 2013). "The CXCR4/C-X-C motif chemokine ligand 12 (CXCL12) signaling axis regulates lung cancer cell migration through the activation of Ras-related C3 botulinum toxin substrate 1 (RAC1), MMPs and multiple signaling pathways, including extracellular regulated protein kinase (ERK) and NF-κB." (PMID 41429896, 2025). "Fibrinogen-like protein 2 (Fgl2), a pleiotropic cytokine affecting multiple cellular functions, was found to be able to increase the aggregation of MDSCs through CXCL12 in lung cancer, and also induced the activation and pro-tumorigenic phenotype of CAFs, which are the main source of CXCL12 in TME." (PMID 40244052, 2025). "For the step-wise metastatic mechanism driven by CXCR4/CXCL12 in lung cancer, see Section 2.1." (PMID 41383468, 2025). "Therefore, inhibition of the CXCL12/STAT3 axis is a promising strategy for the treatment of lung cancers and other CXCL12-dependent malignancies." (PMID 40199862, 2025). "Additionally, ELISA further confirmed that the expression level of CXCL12 in the culture supernatant of COX6A1-knockdown lung cancer cells was significantly reduced." (PMID 40331946, 2025). "Additionally, CXCL12/CXCR4 is believed to be involved in angiogenesis in lung cancer, and high expression of CXCR4 has been significantly associated with bone metastasis." (PMID 38711158, 2024). "We first detected CXCL12 released from fibroblasts and lung cancer cells." (PMID 39759028, 2024).
lung carcinoma (continued). "In addition to IL6, the promoting effect of CAFs on EMT programming in lung cancer cells is also mediated by the secretion of CXCL12 and high mobility group box 1 (HMGB1), which activate the CXCR4/β-catenin/PPARδ and NFκB signaling pathways, respectively." (PMID 38139154, 2023). "Inhibiting CXCL12/CXCR4 axis by CXCR4 antagonists can be a value treatment option in lung cancer." (PMID 35729596, 2022). "Interestingly, the estrogen receptor α promotes cancer cell invasion via the increase of and cross-talk with infiltrated macrophages through the CCL2/CCR2/MMP9 and CXCL12/CXCR4 signaling pathways at least in lung cancer." (PMID 34833360, 2021). "Therefore, it is essential to produce adequate evidence on the therapeutic role of CXCL12/CXCR4 in lung cancer and bone metastasis." (PMID 34722241, 2021). "The results revealed that THP‐1 cells might express higher CXCL12 compared with lung cancer A549 and H1299 cells at mRNA levels (left), which is also confirmed through western blot on protein level (right)." (PMID 32356397, 2020). "Firstly, primary lung cancer cells can secrete exosomes which could induce pre-metastatic niche formation and increase the expression of CXCL12." (PMID 33129326, 2020). "Furthermore, ERα‐increased macrophage infiltration can induce a positive feedback mechanism to increase lung cancer cell ERα expression via the up‐regulation of the CXCL12/CXCR4 pathway." (PMID 32356397, 2020). "CXCL12 is involved in cell proliferation and brain metastasis in lung cancer patients." (PMID 30935067, 2019). "For instance, it was shown in a lung cancer model that IR-induced ROS upregulates the C–X–C motif chemokine receptor type 4 (CXCR4) which then senses its ligand C-X-C motif chemokine ligand 12 (CXCL12)." (PMID 31234336, 2019). "Furthermore, the challenges and potential benefits of incorporating drugs that target CXCL12/CXCR4 into immune-based lung cancer therapeutic protocols are discussed." (PMID 30257500, 2018). "Study indicated that miR-101 could repress lung cancer invasion and proliferation by inhibiting interaction of fibroblasts and cancer cells by directly targeting CXCL12." (PMID 27911279, 2017). "Cxcl12, which was shown to be associated with lung cancer, was not significantly changed in the BaP-treated mice." (PMID 26565418, 2015). "Expression intensity of CXCL16/CXCR6 and CXCL12/CXCR4 protein in human lung cancer tissues." (PMID 24897301, 2014). "The current study also investigated the metastatic potential of lung cancer cell line A549 in response to CXCL12, which may be reduced by the downregulation of CXCR4 expression by the pBSilence1.1 vector, as determined by the Transwell assay." (PMID 24944647, 2014). "CXCR7 is a recently described second receptor for CXCL12 and was shown to promote lung cancer growth in vivo but this receptor might rather modulate CXCR4-mediated responses than act as an independent CXCL12 receptor." (PMID 19455144, 2009). "Furthermore, the CXCR4 antagonists suppressed the growth of lung cancer growth: Peptide R prevented the recruitment of metastasis-initiating cells and inflammatory monocytes toward CXCL12-enriched sites and AMD3100 reduced the progression of cancer in orthotopic SCLC mouse model." (PMID 39114657, 2024). "Moreover miR-101 is downregulated in CAFs of lung cancer which targets the CXCL12 expression thus overexpression of this miRNA could suppress the CAFs to promote cancer cell proliferation." (PMID 36620544, 2022). "In a mouse model of lung cancer, CXCL12 could recruit tumor-promoting myeloid CD11b+ cells." (PMID 28630636, 2017). "Our in vitro experiments demonstrated that COX6A1 knockdown in lung cancer cells led to the upregulation of TGFB2, CXCL12, and FGF2." (PMID 40331946, 2025). "Chemokines, particularly the CCR9/CCL25 and CXCL12/CXCR4 axes, play pivotal roles in lung cancer progression, immune cell recruitment, and tumor microenvironment remodeling." (PMID 40607416, 2025).
lung carcinoma (continued). "CXCR4 receptor binds its ligand, CXCL12 (SDF-1), which is overexpressed in lung cancer cells, and the interaction of this receptor-ligand drives tumor proliferation, migration, and therapy resistance." (PMID 41383468, 2025). "In this study, we demonstrated that lung cancer cells activated CAFs via IGF2-mediated autophagy induction; in return, activated CAFs stimulated lung cancer cell migration and invasion via CXCL12-mediated AKT/NF-κB pathway." (PMID 39759028, 2024). "Novel therapeutic strategies for targeting TAMs in lung cancer include inhibiting of macrophage recruitment with drugs such as CSF1R antibody and C-X-C motif chemokine ligand 12 (CXCL12) inhibitors." (PMID 38974237, 2024). "The Macro-1 cluster was transcriptionally similar to tissue-resident macrophages as reported in primary ccRCC, breast and lung cancers, and expressed markers such as SEPP1, FOLR2, CCL3, CCL4, and CXCL12." (PMID 38281962, 2024). "Conversely, seven of the downregulated hub genes (TLR4, PECAM1, SELP, CXCL12, VWF, KDR, and CD34) showed both low expression and good prognosis in lung cancer patients (p < 0.05)." (PMID 33627711, 2021). "In the present study, we proved that ERα expression in lung cancer cells can promote NSCLC invasion through increase of and cross‐talk with infiltrated macrophages via up‐regulating the CCL2‐ and CXCL12‐involved signal pathways." (PMID 32356397, 2020). "Then secreted CXCL12 enters into the blood circulation and directs CXCR4/CXCR7+ lung cancer cells to the sites of targeted organs." (PMID 33129326, 2020). "More infiltrated macrophages would produce a higher amount of CXCL12, which will act on the CXCR4 receptor on lung cancer cells and lead to activation of p‐ERK1/2 and p‐Akt and a consequent increase of ERα expression in lung cancer cells." (PMID 32356397, 2020). "We found that treatment of lung cancer cells with the A009 extracts resulted in decreased expression of CXC4 in A549 cells and decreased production of CXCL12 in A569 and H1650 cells." (PMID 32224910, 2020). "Our study proved that ERα in lung cancer cells can promote the signal cross‐talk between lung cancer cells and macrophages via the ERα/CCL2/MMP9 and CXCL12/CXCR4 pathways." (PMID 32356397, 2020). "As a principle source of CXCL12, FAP+ CAFs also use the CXCL12-CXCR4 interaction to inhibit the infiltration of T cells in PDAC and lung carcinoma bearing mice." (PMID 31462327, 2019). "Preclinical and clinical studies support the viewpoint that chemokine CXCL12 (stromal cell-derived factor, SDF-1) and it’s receptor CXCR4 play a pivotal role in the progression and metastasis of lung cancers, particularly in non-small cell lung cancer (NSCLC)." (PMID 24897301, 2014). "By contrast, CXCR4-positive cells were highly invasive in response to CXCL12 and the CXCL12 mediated chemotaxis was dose dependent, indicating that the downregulation of CXCR4 had impaired the ability of the lung cancer cells to migrate." (PMID 24944647, 2014). "The results clearly demonstrated that not only CXCR6 and CXCR4 (30/33) but also CXCL12 and CXCL16 (19/33) were coexpressed in both human primary lung caner tissues and lung cancer cell lines." (PMID 24897301, 2014). "It was demonstrated that similar to CXCL12 and CXCR4, CXCL16 and CXCR6 were also coexpressed in human primary lung cancer tissues." (PMID 24897301, 2014). "There is increasing evidence to suggest that the CXCL12/CXCR4 chemokine axis is important for the cell invasion and migration of several types of tumor, particularly lung cancer." (PMID 24944647, 2014). "Furthermore, the expression pattern of CXCL16-CXCR6 was similar to that of CXCL12-CXCR4, the specific staining for both CXCR4 and CXCL12 could also be observed in three lung cancer cell lines despite of the difference of expression intensity in different cells." (PMID 24897301, 2014).
lung carcinoma (continued). "Our study reveals CAFs could promote the conversion of NFs to CAFs-like cells through the CXCL12/STAT3 axis, enhancing tumor growth and metastasis in lung cancer." (PMID 40199862, 2025). "Notably, inhibiting CXCL12 signaling and the STAT3 pathway reduced the conversion of NFs to CAFs, thereby hindering lung cancer progression progression both in vitro and in vivo." (PMID 40199862, 2025). "CXCL12 acts through the C-X-C motif receptor 4 (CXCR4) to promote the recruitment of CXCR4+ neutrophils and leukocytes to the TME as well as to facilitate metastasis of lung cancer." (PMID 40589738, 2025). "In summary, we demonstrated that lung cancer cells activated CAFs via IGF2-mediated autophagy induction and, in return, iCAFs stimulated lung cancer cell migration and invasion via CXCL12-mediated AKT/NF-κB pathway, indicating a positive feedback regulation between lung cancer cells and CAFs." (PMID 39759028, 2024). "Common signal pathways involved with advanced lung cancer, were epidermal growth factor receptor/Kirsten rat sarcoma/anaplastic lymphoma kinase (EGFR/KRAS/ALK) and C-X-C motif chemokine ligand 12/C-X-C motif chemokine receptor 4 (CXCL12/CXCR4)." (PMID 38711158, 2024). "In addition to CCL18, CXCL12 and CCL22 are known to alter the TME in lung cancer by modulating TAM activity." (PMID 39114657, 2024). "C-X-C motif chemokine ligand 12 (CXCL12), also known as the sole ligand of CXCR4, has been verified to be expressed in many tissues and cell types Previous studies demonstrated that the positive expression rate of CXCL12 in lung cancer was 31.3–80%." (PMID 35729596, 2022). "Some studies revealed that CXCL12 protein expression levels were significantly higher in metastatic sites than in primary tumor site, which mediated the metastasis of CXCR4-expressing tumor cells in lung cancer." (PMID 35729596, 2022). "Based on the fact that the expression of CXCR7 and CXCL12 was significantly upregulated in metastatic organs than in primary tumors, we speculate that the mechanism of CXCR7 enhancing lung cancer metastasis may include following steps." (PMID 33129326, 2020). "Together, the interactions between lung cancer cells and macrophages through ERα/CCL2/CCR2/MMP9 and CXCL12/CXCR4 pathways could promote the NSCLC progression." (PMID 32356397, 2020). "CXCL12 is overexpressed in NSCLC cell lines and primary lung cancer and may promote tumor cell migration and growth through the ERK pathway." (PMID 30935067, 2019). "USP17 could be induced by cytokines secreted from macrophages because various cytokines, including TNF-α, IL-1β, IL-4, IL-6, IL-8, IL-10, CXCL12, CCL18, and CCL22, were able to induce USP17 expression in H1299 and D121 lung cancer cells." (PMID 30038267, 2018). "Different factors can also influence CXCL12 and CXCR4 expression in lung cancer." (PMID 23322021, 2013). "However, in lung cancer, CXCR4 overexpression facilitates tumor cells to migrate along chemotactic gradients of its ligand CXCL12 (stromal cell-derived factor 1, SDF-1) toward CXCL12-enriched metastatic niches, where tumor adhesion, survival, and immune escape are enhanced." (PMID 41383468, 2025). "In addition, although CAV1, SMAD7, BMP2, EDN1, and CXCL12 were not significantly different in the prognostic analysis in our study, they also play important roles in the occurrence and development of lung cancer." (PMID 34820377, 2021). "This may explain why our constructed overexpressed CXCR7 A549-GFPLuc-CXCR7 lung cancer cells were treated with certain concentration of CXCL12, with CXCR7 recycling not observed." (PMID 33129326, 2020). "Moreover, through the lentiviral transduction of two different shRNAs (shERα#1 and shERα#2) or the treatment with a selective ERα antagonist, we proved that the regulatory pathway is through the production of macrophage CXCL12 to activate its receptor, CXCR4, on lung cancer cells." (PMID 32356397, 2020).